RAB2A (RAB2A, member RAS oncogene family)
Description:
The small GTPases Rab are key regulators of intracellular membrane trafficking, from the formation of transport vesicles to their fusion with membranes. Rabs cycle between active GTP-bound and inactive GDP-bound states. In their active state, drive transport of vesicular carriers from donor organelles to acceptor organelles to regulate the membrane traffic that maintains organelle identity and morphology. RAB2A regulates autophagy by promoting autophagosome-lysosome fusion via recruitment of the HOPS endosomal tethering complex; this process involves autophagosomal RAB2A and lysosomal RAB39A recruitment of HOPS subcomplexes VPS39-VPS11 and VPS41-VPS16-VPS18-VPS33A, respectively, which assemble into a functional complex to mediate membrane tethering and SNAREs-driven membrane fusion. Required for protein transport from the endoplasmic reticulum to the Golgi complex. Regulates the compacted morphology of the Golgi. Together with RAB2B, redundantly required for efficient autophagic flux.
Synonyms: RAB2; LHX
Tractability: Small molecule: a structure with a bound ligand is known; it has a high-quality binding pocket. PROTAC: ubiquitination databases record sites on it; its protein half-life has been measured; a small molecule that binds it is known.
Target class: Enzyme; Hydrolase
Gene: Protein-coding gene on chromosome 8 (60,516,936 to 60,623,644, forward strand). Ensembl gene ENSG00000104388.
Subcellular location: Endoplasmic reticulum-Golgi intermediate compartment membrane; Melanosome; Endoplasmic reticulum membrane; Golgi apparatus membrane; Cytoplasmic vesicle, secretory vesicle, acrosome; Cytoplasmic vesicle, autophagosome membrane
Pathways (Reactome):
Cell Cycle: Golgi Cisternae Pericentriolar Stack Reorganization
Metabolism of proteins: RAB geranylgeranylation
Gene Ontology:
Molecular function: G protein activity; GDP binding; GTP binding; GTPase activity; protein binding
Biological process: autophagosome-lysosome fusion; endoplasmic reticulum to Golgi vesicle-mediated transport; Golgi organization; macroautophagy; vesicle-mediated transport
Cellular component: endoplasmic reticulum-Golgi intermediate compartment membrane; extracellular exosome; lysosomal membrane; melanosome; nucleus; autophagosome membrane; cytosol; Golgi apparatus; Golgi membrane; acrosomal vesicle; cytoplasm; endoplasmic reticulum membrane
Genetic constraint (gnomAD): Loss-of-function variants: 4 observed, 8.93 expected, observed/expected ratio (o/e) 0.45, 90% interval 0.22 to 1.02. That is too few expected variants to judge how well the gene tolerates losing a copy. Missense variants: 52 observed, 134.35 expected, observed/expected ratio (o/e) 0.39, 90% interval 0.31 to 0.49. Synonymous variants: 45 observed, 49.53 expected, observed/expected ratio (o/e) 0.91, 90% interval 0.71 to 1.16.
Homologues: Orthologues: chimpanzee RAB2A (100% identical), dog RAB2A (100% identical), macaque RAB2A (99% identical), rat Rab2a (99% identical), mouse Rab2a (99% identical), zebrafish rab2a (98% identical), pig RAB2A (95% identical), Drosophila melanogaster Rab2 (90% identical), Caenorhabditis elegans unc-108 (89% identical), tropical clawed frog rab2a (82% identical), guinea pig RAB2A (81% identical). Paralogues in human: RAB2B (85% identical), RAB14 (56% identical), RAB4A (52% identical), RAB4B (51% identical), RAB11B (47% identical), RAB11A (46% identical), RAB18 (42% identical), RAB1A (42% identical), RAB1B (42% identical), RAB39A (41% identical), RAB43 (41% identical), RAB37 (40% identical), and 56 more.
Diseases named in the same sentence as RAB2A in open-access papers:
RAB2A is named in the same sentence as 42 diseases in open-access papers, as found by Europe PMC text mining. Sharing a sentence is not in itself a finding about the gene and the disease. The quoted sentences say what the papers report.
breast carcinoma (15 papers, 2017 to 2025). "For instance, gene amplification and overexpression of Rab2A promoted breast cancer stem cell expansion via Erk1/2 activation and was associated with poor clinical outcome in patients with breast carcinoma." (PMID 32823947, 2020). "Rab2A is reported to participate in the occurrence and invasion of a variety of cancers, especially breast cancer." (PMID 35974003, 2022). "In human breast cancer cell lines, the expression of constitutively active RAB2A increased the size of RAB7-positive vesicles." (PMID 34714330, 2021). "Furthermore, by activating the extracellular signal-regulated kinase 1/2 (ERK1/2) signaling pathway, RAB2A was found to promote breast cancer stem cells and tumorigenesis in vitro and in vivo." (PMID 40821113, 2025). "High Rab2A expression is found in human breast cancer suggesting Rab2A could be an independent predictor of disease recurrence in breast cancer patients." (PMID 38695990, 2024). "For example, RAB2A plays a role in the activation of breast cancer stem cells which induces tumors." (PMID 34777562, 2021). "Furthermore, Rab2A interacts with and activates Erk1/2, resulting in increased Zeb1 expression and β-catenin nuclear accumulation, which in turn promotes breast cancer stem cells functions and tumorigenesis." (PMID 30158579, 2018). "Moreover, Rab2A promotes breast cancer stem cell expansion through binding to Erk1/2 and subsequently activating Erk signaling." (PMID 30158579, 2018). "Interaction between Rab2 and HOPS is present in Drosophila and in cells where human Rab2A promotes an invasive program of breast cancers." (PMID 37443788, 2023). "The results showed that DYNLT1, IMMT, RAB2A, and SLC25A5 were unfavorable factors for breast cancer prognosis in the lipid metabolic pathway." (PMID 35919504, 2022). "Rab2A also controls MT1‐MMP endocytic trafficking and Golgi transport of E‐cadherin in the acquisition of a mesenchymal invasive program to promote breast cancer dissemination." (PMID 34401050, 2021). "Rab2a regulates MT1-MMP endocytic recycling and the transport of E-cadherin to the Golgi to promote cell invasion in breast cancer." (PMID 34141705, 2021). "Additionally, a quantitative proteomics analysis of CY-9d-treated breast cancer cells revealed some potential Raf1 and ERK1 interacting proteins in breast cancer cells, such as HSP90, PAK4 and RAB2A." (PMID 29262632, 2017). "Finally, some potential Raf1 and ERK1 interacting proteins in breast cancer cells were detected, such as HSP90, PAK4 and RAB2A." (PMID 29262632, 2017). "For example, increased expression of the small GTPase Rab2A was found in breast cancer tissue compared with adjacent normal breast tissue and was significantly associated with poor prognostic markers manifesting Rab2A as an independent predictor of disease recurrence in breast cancer patients." (PMID 37293129, 2023).
COVID-19 (4 papers, 2020 to 2025). A disease caused by infection with severe acute respiratory syndrome coronavirus 2. "A recent study demonstrated that increased expression of RAB2A was linked to more severe COVID-19 outcome due to its role in viral replication." (PMID 40208878, 2025). "Consistent with our study, a meta-analysis of GWAS revealed that RAB2A (rs13276831) was associated with severe COVID-19, and more expression of RAB2A was associated with worse disease." (PMID 37932299, 2023). "Further experiments are required to explore the effectiveness of CID1067700 in targeting RAB2A in treating COVID-19." (PMID 37932299, 2023). "Even though few potential drugs have been found to target FUBP1 and RAB2A, using RNA-binding proteins to treat COVID-19 is still promising." (PMID 37932299, 2023). "Combining risk genes from the HGI with RBPs, we identify two COVID-19 risk loci that regulate the expression levels of FUBP1 and RAB2A in the lung." (PMID 37932299, 2023). "Further studies such as CRISPR are needed to clarify in which process the anti-viral role of FUBP1 and the pro-viral role of RAB2A play in COVID-19." (PMID 37932299, 2023). "Here, we prioritise eight robust (e.g., ELF5) or suggestive but unreported (e.g., RAB2A) candidate protein mediators of COVID-19 outcomes by integrating results from the COVID-19 Host Genetics Initiative with population-based plasma proteomics using statistical colocalisation." (PMID 35970849, 2022). "The risk locus rs2875968 spans three genes (RAB2A, LINC01301, and CA8), none of which have strong prior evidence implicating them in COVID-19 physiopathology." (PMID 40208878, 2025). "The results showed that FUBP1 and RAB2A are expressed in several types of nasopharyngeal epithelial cells, including FOXN4+ cells, squamous cells, ciliated cells, and secretory cells, in the upper respiratory tract of COVID-19 patients, especially the vRNA+ group." (PMID 37932299, 2023).
bladder cancer (3 papers, 2015 to 2023). "A research of bladder cancer in vitro showed miR-381-3p inhibits the progression of bladder cancer cells by binding to RAB2A (Ras-Related Protein Rab-2A)." (PMID 36856518, 2023). "The miR-381-3p/RAB2A axis induces cell proliferation and inhibits cell apoptosis in bladder cancer." (PMID 34838011, 2021).
Obesity (3 papers, 2022 to 2025). Accumulation of substantial excess body fat. "Collectively, these results demonstrate that hepatic Rab2A deficiency enhances thermogenic gene expression in adipose tissue and protects against diet-induced obesity." (PMID 41314545, 2025). "Mechanistically, hepatic Rab2A inhibition protected mice from high-fat diet–induced obesity and was associated with markedly elevated circulating FGF21, the phenotype largely rescued by adenovirus-mediated knockdown of either CREBH or APOB." (PMID 41314545, 2025). "Our studies also showed that inhibition of Rab2A expression alleviated hepatic lipid deposition in western diet-induced obesity (DIO) mice by reducing the protein level of PPARγ and the expression of PPARγ target genes." (PMID 35061665, 2022).
glioma (2 papers, 2017 to 2025). A benign or malignant brain and spinal cord tumor that arises from glial cells (astrocytes, oligodendrocytes, ependymal cells). "Additionally, miR-192 suppresses tumor growth in brain cancers, targeting RAB2A in glioblastoma multiforme, ZEB2 in glioma, and DHFR in medulloblastoma." (PMID 40087755, 2025).
schizophrenia (2 papers, 2024 to 2025). A major psychotic disorder characterized by abnormalities in the perception or expression of reality. "About half of them has been previously associated with schizophrenia in humans, such as Olig1, Fgfr1, Gpr17, Gna12, Abca2, Sox1, Dpm2, and, as a locus for de novo mutations, Rab2a." (PMID 39825014, 2025). "An RNA sequencing analysis of the PFC suggested a dysregulation of numerous schizophrenia related genes including Olig1, Fgfr1, Gpr17, Gna12, Abca2, Sox1, Dpm2, and Rab2a in the rat model of psychosis." (PMID 39825014, 2025).
Chlamydia infections (1 paper, 2009). "Since Rab2A controls membrane trafficking in the secretory pathway, the function of Rab2A during Chlamydia infections was also addressed in our study." (PMID 19816566, 2009).
colon cancer (1 paper, 2021). "miR-192 also benefits the prognosis of colon cancer patients by regulating SRPX2, Rab-2A, RhoA-ROCK-LIMK2, farnesoid X receptor, RB1/E2F1 pathway, and NOD2." (PMID 33614788, 2021).
Crohn disease (1 paper, 2016). A gastrointestinal disorder characterized by chronic inflammation involving all layers of the intestinal wall, noncaseating granulomas affecting the intestinal wall and regional lymph nodes, and transmural fibrosis. "Moreover, it was recently reported that LRRK2 and Rab2a regulate Paneth cell function, which is compromised in Crohn’s disease." (PMID 26824392, 2016).
Globozoospermia (1 paper, 2021). Any structural anomaly of the acrosome resulting in a round sperm head. "Further analysis of the function of FAM71F1 and its relationship with membrane trafficking-related proteins, such as RAB2A and RAB2B, will help to understand the mechanism that regulates acrosome formation and identify causative genes of globozoospermia." (PMID 34714330, 2021).
Hepatic steatosis (1 paper, 2022). Steatosis is a term used to denote lipid accumulation within hepatocytes. "The results from this study reveal the novel functions of Rab2A regulated by the AMPK-TBC1D1 axis in hepatic steatosis." (PMID 35061665, 2022).
hyperlipidemia (1 paper, 2024). "Building upon the observed relationship between Rab2A and serum lipid under both “Random feed” and “Fasted” conditions, we further investigated whether Rab2A deficiency in hepatocytes could also confer resistance against hyperlipidemia induced by high-fat-high-cholesterol diet (HFHCD)." (PMID 39496977, 2024).
invasive breast carcinoma (1 paper, 2023). A carcinoma that infiltrates the breast parenchyma. "DYNLT1, IMMT, RAB2A, and SLC25A5 are independent prognostic factors for invasive breast carcinoma and confer a poor prognosis 2)." (PMID 37179822, 2023).
melanoma (1 paper, 2022). A malignant, usually aggressive tumor composed of atypical, neoplastic melanocytes. "A gene expression array confirmed a positive correlation between ADCK2 expression and RAB2A (Ras-related protein Rab-2A) and MYL6 expression in different melanoma cell lines." (PMID 35205819, 2022). "RAB2A is a known oncogene in many cancers but has not yet been studied in melanoma." (PMID 35205819, 2022).
overnutrition (1 paper, 2022). An imbalanced nutritional status resulting from excessive intake of nutrients. "This study shows that overnutrition suppresses the phosphorylation of AMPK and TBC1D1, augmenting the level of GTP-bound Rab2A and increasing the stability of PPARγ, which ultimately promotes the hepatic accumulation of lipids." (PMID 35061665, 2022).
sarcoma (1 paper, 2024). A usually aggressive malignant neoplasm of the soft tissue or bone. "Moreover, proliferation index of sarcoma is both correlated with protein expression of RAB2A and autophagy pathway GSVA enrichment scores." (PMID 38360860, 2024).
cancer (8 papers, 2018 to 2025). A tumor composed of atypical neoplastic, often pleomorphic cells that invade other tissues. "Notably, Rab2A acts as an oncogenic-like protein to promote cancer stemness via disrupting the cancer signaling pathway rather than disrupting the trafficking pathways." (PMID 30158579, 2018). "Interestingly, these three genes (RAB1B, RAB2A, and RAB18) have been studied in several malignant tumors." (PMID 32432324, 2020). "Clathrin, caveolin, Rabs (Rab4, Rab5A, Rab1A, Rab2A) as well as their effectors (Rab25, Vav1, Rab coupling protein,cdc42, VSP39), can contribute to the processes of cancer cell survival and metastasis, and cancer stem cell emergence." (PMID 29409507, 2018).
tumor (8 papers, 2017 to 2024). "Importantly, by performing comparative analysis, we found the RAB signaling pathway was dominantly enriched in DDLPS, and further illustrated that RAB2A might lead to tumor cell proliferation of DDLPS by increasing autophagy process." (PMID 38360860, 2024). "We found that DYNLT1, IMMT, RAB2A, and SLC25A5 were tumor biomarkers to assess the prognosis of BRCA patients, and all of them were high-risk genes, and the parameters indicated that 4 genes would make the prognosis of BRCA poorer." (PMID 35919504, 2022). "RAB1B (P<1E-12), RAB2A (P<1E-12), and RAB18 (P=2.7611E-09) were significantly up-regulated in primary tumor tissue (n=1 097) compared with that in normal tissue (n=114)." (PMID 32432324, 2020). "In line with this, a recent study has shown that Vps39, along with Rab2a, controls exocytosis of late endosomal MT1-MMP, an essential metalloprotease required for extracellular matrix remodeling and tumor invasion." (PMID 28325809, 2017).
infection (5 papers, 2009 to 2023). The state of being infected such as from the introduction of a foreign agent such as serum, vaccine, antigenic substance or organism. "Infection with wild-type bacteria caused a redistribution of GFP-GS15 in BMMs, as previously shown, which was partially dependent on Rab2a since its depletion (99.4% depletion) decreased GS15 redistribution induced by wild-type bacteria." (PMID 32234817, 2020). "To validate the interaction of SidM and LidA with the identified Rab GTPases during infection, we performed co-immunoprecipitations of the effectors with Rab2A, Rab5C, and Rab10." (PMID 26755725, 2016). "To assess the effect of the Rab family on RSV replication, we depleted Rab1a, Rab2a, Rab4a, Rab5a, Rab6a, Rab7a, Rab8a, Rab9a, and Rab11a by treating A549 cells with specific siRNAs (or control siRNA) for 24 h, followed by infection with purified RSV A2 and incubation for another 36 h." (PMID 33504607, 2021).
RAB2A also shares sentences with these, for which no sentence is quoted: Ataxia (1 paper); autism spectrum disorder (1); bipolar disorder (1); brain tumors (1); cataract (1); cervical cancer (1); CHARGE syndrome (1); chlamydial infections (1); glioblastoma multiforme (1); inflammatory bowel disease (1); lipoblastoma (1); malaria (1); male infertility (1); metabolic disease (1); microcephaly (1); nonalcoholic fatty liver disease (1); osteoporosis (1); pancreatic cancer (1); Parkinson disease (1); psychosis (1); Sepsis (1); vaginal cancer (1); vaginitis (1).